TNF (tumor necrosis factor)
Diseases named in the same sentence as TNF in open-access papers (continued):
Sharing a sentence is not in itself a finding about the gene and the disease.
migraine (continued). "The aim of this study was to investigate whether functional polymorphisms in the IL-1 family (IL-1α, IL-1β and IL-1RN), IL-6 and TNF-α genes may influence the response to oral NSAID administration or triptans during migraine attacks." (PMID 36614097, 2022). "Besides, TNF-α and IL-6 showed that increased plasma levels have already been demonstrated in migraine patients compared to healthy controls." (PMID 35784726, 2022). "Although the exact pathophysiology of migraine is not fully understood, the serum of individuals who suffer from migraine contains elevated amounts of pro-inflammatory cytokines such as tumor necrosis factor-alpha (TNF-α) and interleukin (IL)-1." (PMID 36168375, 2022). "CGRP may lead to the release of pro-inflammatory cytokines, and the levels of interleukine-6 (IL-6) and tumor necrosis factor alpha (TNF-α) were increased in the plasm of migraine patients." (PMID 35784726, 2022). "Altered interleukin and TNFα levels in migraine have been demonstrated in the literature." (PMID 36050647, 2022). "A further understanding of the role of TNF-α may have therapeutic implications for future migraine treatment." (PMID 36614097, 2022). "As is true of AR, midfacial or nasal pain during migraine may be accompanied by the release of a variety of neuropeptides, such as histamine, substance P, NO, vasoactive intestinal peptide, TNF-α, and others." (PMID 36010131, 2022). "However, the frequency of the TNF-α-308 GG genotype was lower in the patient group than in the control group, suggesting a link between migraine and inflammation." (PMID 34445635, 2021). "Emodin could treat migraine by inhibiting the production of NO in migraine rats, the release of TNF-α inflammatory factors, the production of vasoactive peptide SP, CGRP, and the expression of PKG protein." (PMID 34744735, 2021). "Furthermore, plasma and cerebrospinal fluid levels of neuropeptides, histamine, proteases, and pro-inflammatory cytokines (e.g., TNFα, IL-1β) are elevated during migraine attacks, suggesting that neuroimmune interactions contribute to migraine pathogenesis." (PMID 35052756, 2021). "Therefore, vasoactive factors such as NO, CGRP, SP, TNF-α and cGMP can be used as important biochemical indicators for the diagnosis of migraine." (PMID 34744735, 2021). "So, CGRP, TNF-α, and IL-1β were proposed as therapeutic targets of migraine." (PMID 33995549, 2021). "TNFα can trigger tissue edema and immune cell infiltration and can influence the reactivity of signal nociceptors to the brain and increase blood levels during headaches, playing a crucial role in the genesis of migraine." (PMID 35052756, 2021). "Furthermore, serum concentrations of IL-1β, IL-6, IL-8, and TNF-α were found increased during migraine attacks." (PMID 34112082, 2021). "In summary, the gut microbiota dysbiosis might contribute to prolongation of migraine-like pain by upregulating TNFα level in the trigeminal nociceptive system." (PMID 34576297, 2021). "In contrast, contradictory evidence for the role of TNF-α in migraine has been reported." (PMID 32121467, 2020). "In the migraine with aura subgroup, only 1 (TNF-α/rs1800629) and 3 (MTHFR/rs1801133, ESR1/rs1801132 and TNF-α/rs1800629) genetic variants was noteworthy in FPRP at the prior probability of 0.05 with a statistical power to detect an OR of 1.2 and 1.5, respectively." (PMID 32046629, 2020). "On the other hand, as mentioned, proinflammatory cytokines such as TNF-α, IL-1β and IL-6 could also affect nociceptive responses in the trigeminal pathway and play a role in migraine pain initiation." (PMID 32054443, 2020). "Platelets activation may be involved in triggering migraine attacks through 5-HT metabolism, NO, and a number of pro-inflammatory cytokines, including interleukins 1, 6, and 8 (IL-1, IL-6, IL-8) and TNF-α." (PMID 31722730, 2019).
migraine (continued). "Additionally, decreased levels of cortisol and elevated levels of pro-inflammatory cytokines (e.g. tumor necrosis factor-alpha, interleukin-6) in patients with PTSD have been suggested to be linked to migraine." (PMID 28685258, 2017). "To clarify this association, we performed a meta-analysis of case-control studies to evaluate whether the TNF –308G>A and NOS3 +894G>T polymorphisms confer genetic susceptibility to migraine." (PMID 26098763, 2015). "Nevertheless, the reverse effects were observed in studies of the TNF –308G>A polymorphism and migraine without aura (MO)." (PMID 26098763, 2015). "Subgroup analyses suggested that the “A” allele of the TNF –308G>A variant increases the risk of migraine among non-Caucasian populations, which was driven by associations for MO." (PMID 26098763, 2015). "Among studies investigating the TNF –308G>A polymorphism, stratified analysis by ethnicity suggested an increased risk of migraine among non-Caucasians." (PMID 26098763, 2015). "Subgroup analyses suggested that the “A” allele of the TNF –308G>A variant increases the risk of migraine among non-Caucasians (dominant model: pooled OR = 1.82; 95% CI 1.15 – 2.87)." (PMID 26098763, 2015). "We performed a meta-analysis of case-control studies to evaluate whether the TNF –308G>A and NOS3 +894G>T polymorphisms confer genetic susceptibility to migraine." (PMID 26098763, 2015). "Despite the currently incomplete definition of the exact pathophysiology of migraine, cytokine-related genes, such as tumor necrosis factor (TNF), interleukin-1β (IL-1β) and IL-10, are known genetic candidates contributing to the predisposition towards migraine development." (PMID 24959879, 2014). "A previous investigation into the associations between TNF gene polymorphisms and migraine presented the discoveries indicating that there was no overall association between the 252A>G polymorphism and migraine." (PMID 24959879, 2014). "A recent study has also linked TNFα to meningeal nociception, where it was suggested that TNFα functioned through TNFRI & TNFRII on nociceptive neurons and was associated with the “throbbing” sensation significant in migraines." (PMID 24592205, 2014). "TNF-α is a proinflammatory cytokine that is related with migraine." (PMID 24453913, 2013). "Clinical and experimental studies have proposed that a neuroinflammatory state of meninges, enriched with inflammatory cells releasing pain mediators like TNFα, known to play an important role in chronic pain, might contribute to migraine attacks." (PMID 23577145, 2013). "Using primary cultures of WT or KI trigeminal ganglia, we investigated whether soluble compounds that may contribute to initiating (or maintaining) migraine attacks, such as TNFα, CGRP, and BDNF, might be responsible for increasing P2X3 receptor responses." (PMID 23577145, 2013). "The gain of function TNF-α-308 A and IL-1β + 3953 T allele gene polymorphisms are elevated in patients with migraine without aura, although the implications are unclear." (PMID 23181051, 2012). "Variants in the genes coding for TNF-alpha and the closely related TNF-beta have been shown to modulate cytokine levels of TNF-alpha and TNF-beta prompting investigations of various polymorphisms in these genes with respect to their role in migraine." (PMID 22072275, 2012). "TNF-alpha and TNF-beta have both been previously associated with migraine." (PMID 19018300, 2008). "This is supported by the findings showing that patients with migraines have higher levels of IL-6, interleukin 8 (IL-8), and tumor necrosis factor (TNF-α) compared to healthy individuals, indicating that these pro-inflammatory cytokines may play a role in the development of a migraine." (PMID 40002876, 2025).
migraine (continued). "For days with migraine in the past 4 weeks, the difference in the change from baseline between the sham diet and the true diet groups was significantly attenuated after adjusting IL-6 and TNF-α (i.e., p-value = 0.0098 for the unadjusted model vs. p-value = 0.0757 for the adjusted model)." (PMID 41473187, 2025). "Mechanistic insights suggested that postoperative weight loss led to hormonal changes (e.g., lowered calcitonin gene-related peptide levels) and reductions in pro-inflammatory cytokines (such as IL-6 and TNF-α), all of which may contribute to the observed migraine relief." (PMID 41278056, 2025). "After adjusting for IL-6 and TNF-α in the exploratory analysis, the positive effect of diet intervention on the severity of migraine and its comorbidities (except MSQ) was reduced, which supports our hypothesis that IL-6 and TNF-α partially mediated the causal pathway." (PMID 41473187, 2025). "A meta-analysis of 6,682 migraineurs reported that TNF-308G>A polymorphism may be a genetic susceptibility factor for migraine among non-Caucasians." (PMID 38913047, 2024). "This suggests that aCL and β2GPI may contribute to migraine with aura via TNF-α mediated pathways." (PMID 39087012, 2024). "However, after adjusting for DBP (OR [95% CI]: 1.4120 [0.8487–2.3493], p = 0.1840) and TNFα (OR [95% CI]: 1.2411 [0.8352–1.8443], p = 0.2852), no discernible association was detected between the genetic predisposition to migraine and the risk of AD." (PMID 38903170, 2024). "Hence, the increased concentrations of interferon-gamma and TNF-α, which control CGRP synthesis, may explain the association between migraine and celiac disease." (PMID 38731144, 2024). "Our results indicated that the effect of migraine in increasing the risk of AD development might be mediated by TNFα, while IL-1α, IL-1β, and IL-6 do not play a role in this process." (PMID 38903170, 2024). "Furthermore, comprehensive genetic analysis using GWAS has identified not only genes encoding CGRP and 5-HT1F receptors but also genes involved in the production of TNF-α and IL-6 and regulating apoptosis and inflammatory responses as candidate genes for migraine." (PMID 37176049, 2023). "For example, the results may not be consistent with the observation that TNF gene variants are more common in Asian patients with migraine." (PMID 37176049, 2023). "Interestingly, in animal models, gut microbiota dysbiosis contributes to chronicity of migraine-like pain by upregulating TNF-α level in the trigeminal nociceptive system, while probiotic administration significantly inhibited the antibiotic-produced migraine-like pain prolongation." (PMID 33958992, 2021). "Various vasoactive peptides (e.g., CGRP, PACAP, and substance P (SP)) and inflammatory mediators (e.g., nitric oxide (NO), IL-1β, and TNF-α) which are proposed to be involved in migraine pathogenesis, could impose their effects mainly through inducing neuroinflammation induction in the CNS." (PMID 33653409, 2021). "We recorded migraine/headache characteristics every 10 min until 90 min after infusion start and collected blood to investigate mast cell degranulation and the inflammation markers tryptase and tumor necrosis factor-alpha (TNF-alpha) before and after infusion of PACAP38." (PMID 30238173, 2018). "Even if LPS cannot be considered a migraine-provoking tool, it is often used to investigate microglia activation, as its intraperitoneal (i.p.)injection induces an early (1 h) rise in TNFα mRNA followed by strong expression of TNFα protein by macrophages a few h later." (PMID 23326332, 2013). "In view of previous reports that neuroinflammation might be contributory to sensitize neurons in migraine attacks, we first investigated whether mouse trigeminal ganglion neurons could respond to TNFα as evidenced by their expression of the TNFα receptor TNFR2." (PMID 23577145, 2013).
migraine (continued). "Nitroglycerin (NTG) triggers pathological vasodilation in the migraine mice model, accompanied by elevated Mt2, nitric oxide (NO), and pro‐inflammatory markers (CGRP, IL‐6, TNF‐α), alongside neuronal activation." (PMID 41194575, 2025). "At the end of 12 weeks, the true diet group had a larger reduction in questionnaires of migraine (except for MSQ), gastrointestinal symptoms, and poor sleeping, as well as food-specific positive IgG, IL-6, TNF-α, and CGRP in the serum." (PMID 41473187, 2025). "High levels of TNF-α have the inherent ability to enhance damage related to neurological diseases, which takes part in the body’s immune regulation and inflammatory response, so inhibiting its signal transduction may be an effective strategy for treating migraines." (PMID 41009787, 2025). "It should be noted that aSMase activity can be increased by the action of pro-inflammatory stimuli, such as Tumor Necrosis Factor α (TNF-α), Interleukin-1β (IL-1β) or cytosolic phospholipase A2 (cPLA2), also involved in migraine." (PMID 40002346, 2025). "Experimental validation confirmed Mt2's dual regulatory function: its inhibition reduced NOS2 expression—a key mediator of vascular tone—and concurrently decreased migraine‐related inflammatory markers, including CGRP, IL‐6, and TNF‐α." (PMID 41194575, 2025). "Studies have shown that PTGS2 participates in the pathogenesis of migraines, and the symptoms of migraine patients can be improved by inhibiting the PTGS2 proinflammatory pathway and reducing the levels of TNF-α, IL-2, and IL-6." (PMID 41009787, 2025). "Included studies measured inflammatory cytokines [e.g., interleukins, TNF-α, and C-reactive protein (CRP)] and related them to migraine frequency or transformation." (PMID 41377228, 2025). "The serum level of IL‐1β, IL‐6, TNF‐α, and CGRP in the migraine group were significantly higher than the normal group." (PMID 41496770, 2025). "The endothelial‐specific knockdown of Mt2 suppressed neurovascular inflammatory cascades (NOS2, TNF‐α, IL‐6, CGRP), regulating the cerebrovascular tone and somatosensory cortical neuronal activation, contributing to the migraine‐like pain relief." (PMID 41194575, 2025). "TNF‐α, trigeminal ganglia, and CGRP have been reported to be involved in the mechanism of migraine with aura." (PMID 38346716, 2024). "Similar to our findings, previous studies indicated higher expression levels of proinflammatory cytokine genes or proteins (e.g., IL-1β, IL-6, and TNF-α) in the peripheral blood and trigeminovascular region of animals with NTG-induced migraine." (PMID 38612517, 2024). "Consistent with our research, some studies have found that the transcriptional activity of inflammatory cytokines (IL-6 and TNF-α) and CGRP was increased in trigeminal ganglia, cervical medulla, and pons in NTG-induced migraine model." (PMID 37090989, 2023). "Proinflammatory cytokines, such as interleukin (IL)-1β, IL-6, and tumor necrosis factor-alpha (TNF-α), as well as anti-inflammatory cytokines, such as IL-10, are elevated in patients with migraine and are suggested to play a role in migraine." (PMID 36362765, 2022). "XZR reduced the degranulation of mast cells as well as the levels of CGRP, SP, NO, and proinflammatory cytokines, including TNF-α, IL-1β, and IL-6, suggesting that XZR improved migraine by relieving the neurogenic inflammatory response." (PMID 35928284, 2022). "In an animal model of migraine, the expression of COX-2, MMP9 and TNF-α increased after an NO donor infusion, with expression being more evident in the meningeal blood vessels." (PMID 36614097, 2022). "Meanwhile, previous studies have found that inflammation plays an important role in the pathophysiology of migraine, and the levels of serum inflammatory cytokines, such as CRP, IL-1β, IL-6, and TNF-α are higher in migraineurs compared with healthy controls." (PMID 35493816, 2022).
migraine (continued). "Altered levels of pro-inflammation cytokines in plasma and serum, such as interleukin 1 beta (IL-1β), interleukin 6 (IL-6), and tumor necrosis factor alpha (TNF-α), has been demonstrated the correlation to migraine in both patients and animals." (PMID 35033010, 2022). "This research investigated the behavioral response of emodin to NTG-induced migraine rats; the levels of vasoactive factors NO, CGRP, SP, TNF-α and cGMP; the activity of c-Fos neurons and the expression of PKG protein." (PMID 34744735, 2021). "TNFα, PGE2, IL-6, and IL-1β are proinflammatory cytokines which have been demonstrated in the process of migraine." (PMID 31428213, 2019). "Elevated TNF-α serum levels in humans, even in outside of attacks, confirm a possible role of TNF-α in migraine." (PMID 31870279, 2019). "The purpose of the present study was to investigate the role of CD14 in relation to the expression of TNF-α in monocytes, serum levels of TNF-α and MIP-1 Macrophage Inflammatory Protein-1 (MIP-1) in migraine patients during the interictal period." (PMID 28208835, 2017). "The aim of the present study was to investigate the levels of circulating CD14 in relation to the expression of tumor necrosis factor alpha (TNF-α) in monocytes, and serum levels of TNF-α and macrophage inflammatory protein-1 (MIP-1) in migraine patients." (PMID 28208835, 2017). "Studies in cultured trigeminal neurons showed that migraine pharmacotherapies can both inhibit CGRP transcription and reduce CGRP release, whereas TNF-α can stimulate transcription of this peptide." (PMID 27191890, 2016). "In summary, the general results of our meta-analysis do not support a strong overall effect, but provide statistical evidence that the TNF –308G>A polymorphism in the TNF region may represent a risk for migraine among non-Caucasians and MA among both Caucasians and non-Caucasians." (PMID 26098763, 2015). "TNF could act as an inflammatory mediator in the activation and sensitization of meningeal nociceptors, threshold brain excitability, and propagation of neuronal hyperexcitability, consequently leading to persistent pulsating headache characterized in migraine." (PMID 24959879, 2014). "Inflammatory and immune mediators, including TNF-α, IL-1, CGRP, orexin, and IL-6, are involved in migraine pathogenesis, and substance P, CGRP, and IL-6 are elevated during acute migraine attacks." (PMID 23181051, 2012). "Since TNFSF7 is localized to the same migraine susceptibility area at C19p13 and shows homology to the ligands of the TNF-alpha and TNF-beta genes (both localized at C6p21.3), we decided to also investigate this gene for involvement in migraine." (PMID 19018300, 2008). "Specifically, Mt2 appears to integrate endothelial‐derived nitric oxide production (NOS2), cytokine/chemokine release (TNF‐α/IL‐6), and neuropeptide activity (CGRP) to gate vascular tone regulation and neuronal excitability, ultimately driving migraine‐like behavioral manifestations." (PMID 41194575, 2025). "It was revealed that induction of migraine by NTG caused a significant rise in the mean value of serum NO and c-fos as well as brain tissue levels of CGRP and TNF-α relative to the normal rats group without migraine induction (p < 0.001)." (PMID 39500819, 2025). "Moreover, in the gut, immune cells and inflammatory cytokines produced, such as interleukins (IL-1, IL-6), tumor necrosis factor (TNF-α), and C-reactive protein (CRP), seem to be involved in migraine pain, worsening the severity of attacks." (PMID 39861467, 2025). "TNF-α, trigeminal ganglion and CGRP are involved in the pathogenesis of migraine with aura." (PMID 39087012, 2024). "Additionally, inflammatory markers such as interleukin (IL)-1β, IL-6, and tumor necrosis factor (TNF)-α have been observed to increase, particularly during migraine attack phases." (PMID 39698251, 2024).